GIMD1 (GIMAP family P-loop NTPase domain containing 1)
Tractability: No criterion of Open Targets' tractability assessment is met for any kind of drug.
Gene: Protein-coding gene on chromosome 4 (106,357,392 to 106,368,778, reverse strand). Ensembl gene ENSG00000250298.
Gene Ontology:
Molecular function: GTPase activity; GTP binding
Genetic constraint (gnomAD): Loss-of-function variants: 8 observed, 9.58 expected, observed/expected ratio (o/e) 0.83, 90% interval 0.49 to 1.49. That is too few expected variants to judge how well the gene tolerates losing a copy. Missense variants: 229 observed, 218.81 expected, observed/expected ratio (o/e) 1.05, 90% interval 0.94 to 1.17. Synonymous variants: 80 observed, 80.83 expected, observed/expected ratio (o/e) 0.99, 90% interval 0.82 to 1.19.
Homologues: Orthologues: chimpanzee GIMD1 (98% identical), macaque GIMD1 (94% identical), pig GIMD1 (82% identical), dog GIMD1 (81% identical), rabbit GIMD1 (81% identical), rat Gimd1 (73% identical), mouse Gimd1 (73% identical), tropical clawed frog gimd1 (43% identical). Paralogues in human: GIMAP5 (25% identical), GIMAP7 (24% identical), GIMAP1 (24% identical), GIMAP6 (24% identical), GIMAP8 (23% identical), GIMAP2 (22% identical), GIMAP4 (22% identical).